SETD1A (SET domain containing 1A, histone lysine methyltransferase)
Diseases named in the same sentence as SETD1A in open-access papers (continued):
Sharing a sentence is not in itself a finding about the gene and the disease.
psoriasis (1 paper, 2025). An autoimmune condition characterized by red, well-delineated plaques with silvery scales that are usually on the extensor surfaces and scalp. "The first was SETD1A (rs11640961), which demonstrated opposite directions of effect in psoriasis and PD." (PMID 41465136, 2025).
Sepsis (1 paper, 2024). Sepsis is defined as life-threatening organ dysfunction caused by a dysregulated host response to infection. "SETD1A and MLL1 revealed a high expression and colocalisation within DNA in sepsis patients, corresponding with the in vitro model of LPS-stimulated neutrophils." (PMID 38745328, 2024). "The analysis of neutrophils isolated from blood patients with sepsis revealed the correlation with the in vitro model within the expression of MLL1 and SETD1A, as well as analysis of GO processes positioned by H3K4me3 related to chromatin remodelling." (PMID 38745328, 2024). "Especially, the high signal of MLL1, SETD1A, but also CHD1 and JMJD2A is observed in the course of sepsis which did not correlate with LPS stimulation resulting in MLL1 and STED1A high signal only." (PMID 38745328, 2024).
viral infection (1 paper, 2024). "About 80% of NSCs were infected by lentivirus as indicated by GFP expression and Setd1a levels were diminished at day 5 (3 days after viral infection) with Cre-GFP expression." (PMID 38971831, 2024).
cancer (50 papers, 2014 to 2025). A tumor composed of atypical neoplastic, often pleomorphic cells that invade other tissues. "Our findings demonstrate that loss of SETD1A also drives PARPi resistance in ATM-deficient cancer cells." (PMID 39994444, 2025). "This revealed that BRCA1- and ATM-deficient cancer patients with low SETD1A mRNA expression had poorer overall survival outcomes compared to those with higher levels of SETD1A." (PMID 39994444, 2025). "Research has shown that SETD1A is upregulated in various cancers, and its overexpression is linked to accelerated tumor cell proliferation and invasion, which is often correlated with poor prognosis." (PMID 39620228, 2024). "Many studies have shown that high expression of SETD1A is associated with poor prognosis in many cancer patients, but the mechanism of SETD1A related to the prognosis of cancer patients is different." (PMID 38164353, 2024). "Here we show that loss of SETD1A also confers PARPi resistance in ATM-deficient cancer cells." (PMID 39994444, 2025). "Loss of SETD1A from both BRCA1-deficient and ATM-deficient cancer cells was associated with resistance to Olaparib, explained by partial restoration of homologous recombination." (PMID 39994444, 2025). "Further studies on the hierarchical transcriptional cascade must be conducted to comprehensively understand the SETD1A/E2F4–TAF6 axis and the effects of SETD1A inhibition in cancer." (PMID 40846851, 2025). "Here, we discovered that BOD1L exhibits the highest correlated SETD1A co-dependency in human cancer cell lines." (PMID 38989615, 2024). "EZH2 is a target of SETD1A, which maintains cancer stem cell properties by triggering Wnt/β-catenin pathway activity." (PMID 39712244, 2024). "Applying a genome-scale CRISPR knockout screen, we identified that the H3K4 methyltransferase SETD1A and other members of Trithorax group proteins drive cancer stemness in HCC." (PMID 37581938, 2023). "SETD1A (histone lysine methyltransferase SET domain-containing 1A) is related to the occurrence of various cancers." (PMID 36475064, 2022). "Further, we revealed that SETD1A regulates specific transcription factors required for maintaining the pluripotency of cancer stem cells in TamR BC cells." (PMID 35966598, 2022). "Taken together, targeting of this pathway with a SETD1A inhibitor will provide therapeutic benefits for mammalian cancers and diseases." (PMID 36450243, 2022). "SETD1A is involved in the epigenetic regulation of transcription containing histone lysine methyltransferase, which highly involved in cancer progression." (PMID 36475064, 2022). "As we observed the locus-dependent transcriptional defect after SETD1A degradation, an SETD1A inhibitor will provide a more specific tool for cancer therapy than CDK kinase inhibitors by modulating the CTD code on cancer-associated genes." (PMID 36450243, 2022). "First, to investigate the genome-wide effects of SETD1A in cancer stem cell-specific gene expression, RNA-seq analysis was conducted in TamR cells and TamR-CSCs." (PMID 35966598, 2022). "In colorectal cancer, SETD1A has been reported to interact with β-catenin to regulate Wnt signaling and promote cancer cell growth." (PMID 34201935, 2021). "In summary, we found that SETD1A regulates cancer stem cell property and cisplatin sensitivity in NSCLC via activating the Wnt/β-catenin pathway." (PMID 34645486, 2021). "Although SETD1A has been proven to activate the Wnt/β-catenin pathway, the interplay between SETD1A and the Wnt/β-catenin pathway in cancer cells remains to be elucidated." (PMID 34645486, 2021). "The ability of cancer stem cells to adopt a quiescent state has emerged as an important driver of drug resistance; thus, we further investigated the effects of SETD1A on chemotherapy sensitivity in NSCLC cells." (PMID 34645486, 2021).
cancer (continued). "Two other studies have demonstrated that SETD1A cooperates with β-catenin to activate the transcription of Wnt/β-catenin target genes in an H3K4me3-dependent manner in embryonic stem cells and cancer cells." (PMID 34645486, 2021). "Depletion of SETD1A induces the tumor-suppressing effect of senescence; therefore, SETD1A appears to be essential for maintaining mitosis and proliferation of cancer cells." (PMID 34201935, 2021). "In this study, we found that SETD1A regulates cancer stem cell property and cisplatin sensitivity in NSCLC cells via activating the Wnt/β-catenin pathway." (PMID 34645486, 2021). "In contrast, functional experiments showed that SETD1A overexpression exhibited opposite effects on cancer stem cell property and cisplatin sensitivity in NSCLC cells." (PMID 34645486, 2021). "Subsequently, we demonstrated that β-catenin overexpression reversed the effects of SETD1A knockdown on cancer stem cell property and cisplatin sensitivity of NSCLC cells." (PMID 34645486, 2021). "In the current study, we demonstrated that SETD1A regulated cancer stem cell property and cisplatin sensitivity in NSCLC cells via activating the Wnt/β-catenin pathway." (PMID 34645486, 2021). "In this study, we found that SETD1A plays an important role in regulating cancer stem cell property and cisplatin sensitivity in NSCLC cells." (PMID 34645486, 2021). "In the current study, we have demonstrated that SETD1A promotes metabolism reprogramming through its interaction with and coactivation of HIF1α to facilitate cancer cell growth and tumorigenesis." (PMID 32291851, 2020). "In > 200 cancer cell lines and in primary circulating tumor cells, SETD1A expression correlates with genes promoting mitosis and cell cycle suggesting a broad role in suppressing senescence induced by aberrant mitosis." (PMID 31253781, 2019). "Intriguingly, we find that enzymes that deposit histone marks associated with gene activation, such as the H3K4 trimethylases MLL1-4 and SETD1A/B, or the H3K36 trimethylase SETD2 are more often repressed and mutated in cancer." (PMID 25484917, 2014). "This, coupled with mixed reports of PARPi efficacy in trials in other cancer backgrounds of HR-deficiency, led us to examine whether loss of the lysine methyltransferase and pro-NHEJ factor SETD1A influenced PARPi efficacy outside BRCA1." (PMID 39994444, 2025). "The H3K4 methyltransferase SETD1A plays an essential role in both development and cancer." (PMID 38989615, 2024). "Additionally, HG-induced cellular proliferation was reduced by SETD1A depletion in Met1 cancer cells, confirming that SETD1A plays a pro-tumorigenic role in breast cancer." (PMID 36707514, 2023). "As migration and invasion are two other key features of pernicious cancer cells, we also detected whether SETD1A could affect cell migration and invasion." (PMID 36707804, 2023). "On the contrary, the knockdown of SETD1A can suppress the proliferation of cancer cells." (PMID 36475064, 2022). "In addition, our previous study demonstrated the involvement of SETD1A in the expression of genes characteristically expressed in TamR cancer cells (for example, EGFR) as well as ERα-mediated target gene expression." (PMID 35966598, 2022). "Additionally, the role of SETD1A in cancer stem cells (CSCs) was investigated using CSCs isolated from tamoxifen-resistant BC cells." (PMID 35966598, 2022). "Furthermore, we demonstrated that SETD1A plays an important role in maintaining cancer stem cell property in NSCLC cells." (PMID 34645486, 2021). "Indeed, this study showed that SETD1A plays an important role in the proliferation, migration, invasion of C4-2B cells, and cancer stem cell formation." (PMID 32629770, 2020). "OCT4 expression in CSCs derived from C4-2B cells was significantly inhibited upon SETD1A depletion, indicating that SETD1A may play a critical role in the proliferation of cancer stem cells of mCRPC." (PMID 32629770, 2020).
cancer (continued). "From these results, we could assume that SETD1A may play an important role in the proliferation of castration-resistant cancer cells." (PMID 32629770, 2020). "Whether deregulation of DNA methylation could also elevate SETD1A expression in proliferating cancer cells remains to be determined." (PMID 31253781, 2019). "To study the role of SETD1A in cancer, we suppressed its expression in cancer cells." (PMID 31253781, 2019). "Notably, misregulation of the Ska complex, SETD1A/B and KDM5 has been linked to the development and progression of many types of cancers, however the mechanisms are unknown." (PMID 40523001, 2025). "However, the role of cytoplasmic SETD1A in cancer progression still needs further investigation." (PMID 34645486, 2021). "Thus, we further investigated whether SETD1A regulates cancer stem cell property and chemotherapy sensitivity in NSCLC via the Wnt/β-catenin pathway." (PMID 34645486, 2021). "For cancer applications, exploiting the senescence phenotype induced by SETD1A inhibition will require identifying additional actionable signaling nodes to suppress escape from senescence, and combinatorial regimens to definitively halt cancer cell proliferation." (PMID 31253781, 2019). "As such, SETD1A, a chromatin modifying enzyme which integrates two fundamentally opposing pathways – proliferation and senescence – provides a druggable node that may provide insight into modulating cancer and aging phenotypes in the future." (PMID 31253781, 2019). "Moreover, the survival of BRCA1- or ATM-deficient cancer patients could be triaged by SETD1A expression, which was not the case for those with deficiencies in BRCA2, nor those with functional copies/levels of these genes." (PMID 39994444, 2025). "SETD1A, a histone lysine methyltransferase, specifically methylates H3K4 and plays an important role in normal and cancer cell functions." (PMID 38164353, 2024). "In humans, the homolog of Set1, SETD1A, plays a role in cancer cell proliferation and tumorigenesis by methylating heat shock protein HSP70 and the nucleocytoplasmic shuttling protein YAP." (PMID 38181050, 2024). "Despite these advances, there is still much work to be done in the fields of SETD1A, NHEJ and histone methylation to enable the development of more tailored treatments to eradicate human cancers." (PMID 37065862, 2023). "High expression of SETD1A, a histone methyltransferase that specifically methylates H3K4, acted as a key oncogene in several human cancers." (PMID 36707804, 2023). "Enforced expression of GATA3 in HCT116 cells inhibited a series of cancer-promoting proteins, DNMT1, SETD1A, SETDB1, FOXM1, MYC, and MSI1." (PMID 34595169, 2021). "For example, DPY30 was significantly positively correlated with SETD1A, SETDB1 and RBBP5, which have been reported to promote the occurrence and progression of cancers." (PMID 34090418, 2021). "Hnf4a expression resulted in a decreased expression of cancer-promoting factors LSD1, SETD1A, PRMT1, FOXM1, FAK, and SNAI1, and also an increased expression of CDH1." (PMID 34595169, 2021). "SETD1A, a member of SET1/MLL family H3K4 methyltransferases, is involved in the tumorigenesis of numerous cancers." (PMID 34645486, 2021). "Western blot analysis showed that the expression of cancer stem cell related genes, such as SOX2, OCT4 and CD133, was reduced following SETD1A knockdown." (PMID 34645486, 2021). "SETD1A, a histone lysine methyltransferase which specifically methylates H3K4, plays important roles in both normal cell and cancer cell functions." (PMID 32291851, 2020).
cancer (continued). "In addition, tumor initiating assay showed that SETD1A knockdown reduced tumor initiating cell proportion in NSCLC cells, indicating a critical role of SETD1A in maintaining cancer stem cell property in vivo." (PMID 34645486, 2021). "Functional experiments showed that SETD1A positively regulated cancer stem cell property and negatively regulated cisplatin sensitivity in NSCLC cells via the Wnt/β-catenin pathway." (PMID 34645486, 2021). "Besides EZH2, typical epigenetic modification enzymes and cancer-promoting factors, SETDB1, G9A, and SETD1A, were inhibited." (PMID 34595169, 2021). "Our results also showed that the expression of cancer stem cell marker genes (e.g., MYC, NANOG, OCT4, and KLF4) was higher in C4-2B cells than that in LNCaP cells and it was markedly decreased by the silencing of SETD1A." (PMID 32629770, 2020). "Moreover, loss/perturbation of EME1 phenocopies SETD1A loss in the absence of both BRCA1 and ATM and led to the restoration of HR, which was supported by data from cancer cell lines." (PMID 39994444, 2025). "HG-induced Nrg1 overexpression was abolished by silencing of P300, Cbp, and Setd1A genes in Met1 cancer cells compared with scrambled (Scrb) shRNA or shRNA non-treated control cells, indicating that P300, CBP, and SETD1A may be associated with Nrg1 enhanceosome assembly." (PMID 36707514, 2023). "Taken together, our study reveals that SETD1A plays a non-enzymatic role in the regulation of RNAPII activity for productive elongation at TSS and suggests a potential therapeutic window for cancers with transcriptional addiction." (PMID 36450243, 2022). "This study reveals a non-enzymatic role for SETD1A in transcriptional pause release and provides insight into the mechanism of RNAPII pausing and its function in cancer." (PMID 36450243, 2022). "Given that SETD1A promotes EME1 transcription in vitro, and that this correlation was observed in cancer genomic datasets, we hypothesised that EME1 downregulation might drive the PARPi resistance observed in the absence of SETD1A." (PMID 39994444, 2025).
tumor (31 papers, 2013 to 2025). "Low SETD1A levels also correlated with decreased progression-free survival in these HR-deficient patients, and with lower tumour mutational burdens." (PMID 39994444, 2025). "It has been reported that SETD1A is associated with cell differentiation, development, and tumor progression." (PMID 37581938, 2023). "SETD1A loss can trigger the efficacy of aging in suppressing tumors; as a result, SETD1A possibly has a critical effect on maintaining tumor cell growth and mitosis." (PMID 36188615, 2022). "Gene Ontology biological process analysis showed that the regulation of TamR-specific genes by SETD1A was enriched in tumor-associated pathways, such as apoptotic process, mitogen-activated protein kinase cascade, and cell migration." (PMID 35966598, 2022). "Conversely, tumor cells expressing SETD1A exhibit enhanced proliferation, as this modifier plays a crucial role in the regulation of mitotic processes, promoting oncogenic behavior." (PMID 39765675, 2024). "Knockout SETD1A cultures have demonstrated that its absence induces cellular senescence, effectively halting cell division and limiting tumor progression." (PMID 39765675, 2024). "We found that anlotinib has a good proapoptotic effect on tumor cells in vitro and in vivo, and its possible mechanism is related to the inhibition of the DNA damage response by disrupting SETD1A." (PMID 38164353, 2024). "Meanwhile, the Ki67 staining results showed that the cell proliferation rate of SETD1A knockdown tumors was lower compared with the control tumor." (PMID 36707804, 2023). "SETD1A knockdown changed the landscape of SEs, resulting in activation of the transcription of SE-driven tumor suppressors, such as ST3GAL4, AKAP12, PTPN1, AQP9, and ANKRD11." (PMID 37581938, 2023). "SETD1A expression was positively correlated with tumor size, tumor encapsulation, and tumor recurrence, which was further validated by univariate and multivariate Cox proportional hazard regression analyses." (PMID 37581938, 2023). "71.42% (15/21) of tumor tissues have high levels of SETD1A compared with adjacent normal ovarian tissues." (PMID 36707804, 2023). "We also showed that SETD1A-depleted TamR cells exhibited significantly reduced tumor growth in a mouse xenograft model." (PMID 35966598, 2022). "The CPTAC (clinical proteomic tumor analysis consortium) analysis showed that SETD1A protein levels were higher in primary NSCLC tissues than in normal lung tissues on the ULCAN website." (PMID 34645486, 2021). "SETD1A‐knockdown and control cells were subcutaneously injected into nude mice, and the xenograft tumor growth rate was monitored, respectively." (PMID 32291851, 2020). "We identified specific H3K4 and H3K9 methyltransferases, such as Mll, Mll3, Setd1a, Ehmt2, Suv39h1, and Setdb1 as biomarkers of residual tumor cells persisting after chemotherapy." (PMID 23520493, 2013). "In addition to its role in gliomas, SETD1A has been found to be overexpressed in patients with breast cancer, leading to increased tumor growth." (PMID 39765675, 2024). "However, in general, there are few studies on the SETD1A-mediated DNA damage response and tumor progression." (PMID 38164353, 2024). "Downregulated SETD1A significantly suppressed tumor growth and reduced tumor size and weight." (PMID 36707804, 2023). "SETD1A knockdown significantly reduced tumor-initiating capacity and CSCs’ frequency." (PMID 37581938, 2023). "Thus, SETD1A is essential to maintain mitosis and proliferation and its suppression unleashes the tumor suppressive effects of senescence." (PMID 31253781, 2019). "All these data suggest that SETD1A may be a tumor oncogene in OV development." (PMID 36707804, 2023).